EPS8L3 (EPS8 signaling adaptor L3)
Synonyms: EPS8R3; FLJ21522; MGC16817; HYPT5; MUHH2
Tractability: Antibody: its Gene Ontology location is reachable by antibodies, with medium confidence.
Gene: Protein-coding gene on chromosome 1 (109,750,078 to 109,764,062, reverse strand). Ensembl gene ENSG00000198758.
Subcellular location: Cytoplasm
Subcellular location (Human Protein Atlas): Vesicles
Gene Ontology:
Molecular function: actin filament binding; guanyl-nucleotide exchange factor activity; protein binding; actin binding
Biological process: regulation of hair cycle; positive regulation of ruffle assembly; regulation of Rho protein signal transduction; Rho protein signal transduction
Cellular component: cytoplasm; plasma membrane; ruffle membrane
Genetic constraint (gnomAD): Loss-of-function variants: 80 observed, 91.61 expected, observed/expected ratio (o/e) 0.87, 90% interval 0.73 to 1.05. The upper end of that interval is the gene's LOEUF score, 1.05, which puts it in group 4 of 6, group 1 being the genes least tolerant of losing a copy. Missense variants: 721 observed, 763.42 expected, observed/expected ratio (o/e) 0.94, 90% interval 0.89 to 1. Synonymous variants: 286 observed, 302.73 expected, observed/expected ratio (o/e) 0.94, 90% interval 0.86 to 1.04.
Homologues: Orthologues: chimpanzee EPS8L3 (99% identical), macaque EPS8L3 (93% identical), pig EPS8L3 (74% identical), rabbit EPS8L3 (74% identical), dog EPS8L3 (74% identical), mouse Eps8l3 (72% identical), rat Eps8l3 (72% identical), tropical clawed frog eps8l3 (36% identical), zebrafish eps8l3b (35% identical), zebrafish eps8l3a (31% identical), Caenorhabditis elegans eps-8 (27% identical), Drosophila melanogaster aru (24% identical), and 2 more. Paralogues in human: EPS8 (32% identical), EPS8L1 (32% identical), EPS8L2 (30% identical).
Diseases named in the same sentence as EPS8L3 in open-access papers:
EPS8L3 is named in the same sentence as 8 diseases in open-access papers, as found by Europe PMC text mining. Sharing a sentence is not in itself a finding about the gene and the disease. The quoted sentences say what the papers report.
pancreatic cancer (2 papers, 2023). "We intended to investigate the role and regulatory mechanism of EPS8L3 in increase the development of pancreatic cancer (PC)." (PMID 36819133, 2023).
alcohol abuse (1 paper, 2018). The use of alcoholic beverages to excess, either on individual occasions ("binge drinking") or as a regular practice. "Interestingly, the variants identified in EPS8L3 (rs148185176), MYH7, CRX (rs139340178), and SELENOO, were also present in two relatives with alcohol abuse (individuals 6 and 18)." (PMID 30379966, 2018).
lung carcinoma (1 paper, 2023). "Results indicated a significant downregulation of CX3CL1, MS4A15, and GSTA1 in lung cancer cells, while EPS8L3, G6PD, KRT6A, and S100P were notably upregulated, in line with the bioinformatics analysis findings." (PMID 37315289, 2023).
cancer (2 papers, 2014 to 2023). A tumor composed of atypical neoplastic, often pleomorphic cells that invade other tissues. "Its precise role in cancer initiation or progression in mice has not been elucidated, largely because it shares redundant biological functions with other family members, namely Eps8L1, Eps8L2 and Eps8L3." (PMID 25359883, 2014).
tumor (2 papers, 2023). "The expression of CIDEC in tumor tissue was significantly lower than that in adjacent normal tissues, while the expression of EPS8L3 and MUC13 was significantly higher in tumor tissues." (PMID 37978443, 2023). "In order to analyze the relationship between EPS8L3 level and clinicopathological indicators of PC patients, qRT-PCR was used to detect the expression of EPS8L3 in tumor specimens of 40 PC patients." (PMID 36819133, 2023). "In this research, qRT-PCR results found that the EPS8L3 level was significantly higher in the PC tumor tissues than that of adjacent ones, and it was in positive correlation with the incidence of metastasis in PC patients." (PMID 36819133, 2023). "Among them, EPS8L3 can participate in tumor development, actin cytoskeleton reorganization, filamentous actin microfilament aggregation via multiple signaling pathways." (PMID 36819133, 2023). "IHC further confirmed the differential expression of CIDEC, EPS8L3 and MUC13 in tumor tissues and adjacent normal tissue." (PMID 37978443, 2023). "CIDEC was significantly down-regulated in tumor tissues, while EPS8L3, MUC13 and PLEKHS1 were significantly highly expressed in tumor tissues." (PMID 37978443, 2023). "In addition, RT-PCR results displayed that CIDEC was significantly reduced in tumor tissues, MUC13 was significantly increased in tumor tissues, EPS8L3 showed an up-regulated tendency, while PLEKHS1 was down-regulated in tumor tissues." (PMID 37978443, 2023). "CIDEC, EPS8L3, MLC13 and PLEKHS1 may be potential prognostic factors for STAD and can be used to assess the level of immune cell infiltration in tumour tissues." (PMID 37978443, 2023).
EPS8L3 also shares sentences with these, for which no sentence is quoted: gastric cancer (1 paper); hypotrichosis (1); liver cancer (1).